BRCA1 (BRCA1 DNA repair associated)
Diseases named in the same sentence as BRCA1 in open-access papers (continued):
Sharing a sentence is not in itself a finding about the gene and the disease.
tumor (continued). "The current evidence points to potential therapeutic opportunities arising from exploiting SMUG1-mediated BER to induce synthetic lethality in combination with PARP and ATR inhibitors, particularly in BRCA1/2-deficient tumours." (PMID 41394509, 2025). "In our cohort, multivariate logistic regression using the unmatched dataset (N = 411) showed that BRCA1/2 mutation status, tumor size > 5 cm, ER-negative tumor, and the use of carboplatin-containing regimens were independently associated with achieving pCR." (PMID 40405286, 2025). "DNA methylation patterns affecting tumor suppressors, exemplified by BRCA1, RASSF1, and PITX2, have consistently been associated with aggressive behavior and poor outcomes in ER-positive and HER2-negative tumors." (PMID 41373752, 2025). "In 26 patients, 27 tumor Tier I or II variants were identified, with 16/27 (59%) being germline pathogenic variants (PV) (13 BRCA1/2; 3 other genes) and 11/27 (41%) somatic variants (9 BRCA1/2; 2 other)." (PMID 41046341, 2025). "Preclinical studies show that genetic or pharmacological inhibition of RANKL can decrease the formation of preneoplastic lesions, slow tumor progression, and reduce mammary tumorigenesis in Brca1-deficient mouse models." (PMID 40243654, 2025). "This suggests that, in the treatment of non‐BRCA1/2‐mutated tumours, HT can transiently suppress BRCA2 protein expression to mimic a BRCA‐deficient state." (PMID 40859871, 2025). "The proportion of tumor BRCA1 or BRCA2 variants in tumor tissue was significantly lower in the AKT pathway-altered group (8.0 vs. 16.2%, p < 0.001)." (PMID 39466567, 2025). "Salem and colleagues showed that the knockdown of BRCA1 in tumor-associated stromal fibroblasts (shBRCA1 fibroblasts) leads to a significant increase in ketone body production." (PMID 40809180, 2025). "Inhibition of GSK3B sensitized tumor response to Olaparib with a significant decrease in tumor volume and weight compared with tumors treated with Olaparib alone in both BRCA1-proficient as well as BRCA1-deficient 4T1 tumors." (PMID 41243969, 2025). "Germline BRCA1/2 mutation carriers and non‐carriers had similar ages of onset, tumor sizes, lymph node statuses, and hormone receptors (HR) and human epidermal growth factor receptor 2 (HER2) status in the CHCAMS cohort (all p > 0.05)." (PMID 40439693, 2025). "Cells with inactivating mutations of the BRCA1 or BRCA2 tumor suppressor genes show increased sensitivity to PARPis." (PMID 40075848, 2025). "Sensitivity to PARPi has been observed in tumor types associated with heritable BRCA1/2 mutations, including pancreatic, breast, ovarian, and prostate cancers." (PMID 40764600, 2025). "In conclusion, DCIS is part of the hereditary breast and ovarian cancer syndrome caused by BRCA1/2 mutations." (PMID 40002208, 2025). "The administration of bardoxolone methyl resulted in a notable delay in tumor development, extending the latency period by an average of 5.2 weeks in the BRCA1-deficient mice." (PMID 40732256, 2025). "Despite their importance in tumor development, there is limited data available on the expression of cell cycle-engaged proteins in BRCA1/2-mutated BC." (PMID 40136510, 2025). "Recently, an in vivo study demonstrated that treatment with ICIs and platinum-based chemotherapy significantly reduces tumor growth and improves survival rates in BRCA1-deficient TNBC mice." (PMID 40904511, 2025). "Access to PARPi therapy requires confirmation of HRD status, typically determined through tumor DNA sequencing to identify BRCA1/2 mutations or specific patterns of genomic instability indicative of HRD." (PMID 40507252, 2025). "In 2005, two landmark studies demonstrated that tumor cells deficient in BRCA1 or BRCA2 exhibit selective sensitivity to small-molecule inhibitors of the PARP family." (PMID 40830526, 2025).
tumor (continued). "Studies have identified that factors such as positive lymph node status, high histological grade, younger age, high tumor burden, and the presence of BRCA1/2 gene mutations are considered high-risk factors for the development of BM." (PMID 40481929, 2025). "Mutations or loss of BRCA1 can render tumor cells more sensitive to platinum-based chemotherapy, making it a key therapeutic target." (PMID 41353219, 2025). "The inhibition of PARP activity has been shown to exert antitumor effects in tumours harbouring BRCA1 or BRCA2 mutations and exhibiting homologous recombination deficiency." (PMID 40337291, 2025). "One possible explanation for these contradictory clinical findings is the complex interplay between BRCA1 deficiency and the tumor microenvironment." (PMID 40870889, 2025). "In the 2000s, a new class of anticancer drugs specifically targeting a tumor cell population emerged: the poly (ADP-ribose) polymerase (PARP) inhibitors (PARPi) that target cells with deficient BRCA1 or BRCA2 proteins." (PMID 39985088, 2025). "Numerous studies have shown that BRCA1 mutations are associated with more aggressive tumor phenotypes, leading to decreased overall survival, higher likelihood of metastasis, and poorer responses to conventional therapies." (PMID 40870889, 2025). "PARP inhibitor (PARPi) specifically targets HR deficiencies, such as BRCA1 mutations, in tumor cells, and loss of NHEJ renders BRCA1 mutant cells resistant to PARPi." (PMID 39844055, 2025). "BRCA1-mutated tumor cells are known to be sensitive to PARP inhibitors due to defects in replication fork stability, and they have shown synergy with chemotherapy." (PMID 40001543, 2025). "Compared with AZD5305, DSB1559 exhibited superior tumor residence time and tumor-to-plasma ratio and significantly reduced tumor growth while enhancing overall survival in a BRCA1-associated immune-competent TNBC model." (PMID 40521389, 2025). "BRCA1 mutation accumulated more tumor mutational burdens and induced the elevation of neoantigen, thereby broadly activating T cells in the TME." (PMID 40904511, 2025). "Overall, a tumor was determined as HRD-positive when either BRCA1/2 mutation status or wGI score was positive." (PMID 40958873, 2025). "CX-5461, a ribosome-targeting inhibitor, has been investigated in phase I and II trials, which have focused mainly on patients with BRCA1/2 deficient tumours." (PMID 40646287, 2025). "In germline pathogenic variant carriers, the location of mutations within BRCA1 or BRCA2 or the retention of the wildtype allele in the tumor can result in a hypomorphic phenotype associated with resistance to platinum-based therapy." (PMID 41255967, 2025). "In contrast, the ID8 isogenic model, with specific Brca1 and Brca2 mutations, reflected patient tumour‐like responses to PARP inhibitor monotherapy and combination therapy." (PMID 40977519, 2025). "Platinum-based chemotherapy, such as carboplatin, is highly effective in BRCA1/2-mutated or HRD tumours, but resistance can develop through BRCA1/2 reversion mutations that restore HRR or epigenetic silencing of pro-apoptotic genes like MLH1." (PMID 40141188, 2025). "The model revealed that BRCA1 mutations were associated with higher inflammatory infiltration and necrosis, as well as off‐center nuclei and pushing tumor margins, while BRCA2 mutations were associated with more active mitotic phases." (PMID 40439693, 2025). "BRCA1/2 mutation carriers showed significantly higher enrichment of immune cells (P < 0.001) and non‐tumor stromal cells (P < 0.001) than non‐carriers." (PMID 40439693, 2025). "Biomarkers such as germline/tumour BRCA1/2 pathogenic variants or tumour HRD provide some patient stratification, potentially improving economic efficiency and patient safety." (PMID 40069561, 2025).
tumor (continued). "Tumor cells deficient in BRCA1 or RAD51, or those with compromised DNA repair mechanisms, cannot effectively repair DNA damage and thus show heightened sensitivity to platinum-based chemotherapeutic agents." (PMID 41353219, 2025). "Forty‐two cases with mutations in BRCA1/2 had been selected, affecting 19 of 24 investigated tumor entities (Group A)." (PMID 40278800, 2025). "In a previous study, using clinical data, we demonstrated that BRCA1/2‐mutated patient tumours respond better to combination PARP inhibition and chemotherapy compared to BRCA‐wildtype patient tumours." (PMID 40977519, 2025). "Recently, a potent PARP inhibitor, senaparib, has been developed and shown to be highly potent in cell viability tests against tumor cells with BRCA1/2 mutations." (PMID 41155174, 2025). "In the GEL dataset, we have classified as HRD+ 17.4% of the cases, compared to only 5.6% BRCA1/2‐deficient tumours." (PMID 40260608, 2025). "In general, the therapeutic rationale of PARP inhibitors relies on synthetic lethality associated with tumor-acquired mutations, most commonly defects in homologous recombination (HR) repair pathways, such as BRCA1/2 mutations." (PMID 41463260, 2025). "The current study evaluates BRCA-deficient HGSC by first focusing on gBRCApv-carriers and then expanding to include somatic mutations and promoter methylation in BRCA1/2, and other key HR genes, as well as evaluating tumor HRD status." (PMID 41255967, 2025). "The most important risk factors are the family history of the tumor (especially the medical history of first-degree relatives) and BRCA1/2 gene mutations." (PMID 40530017, 2025). "One patient had a PD-L1 combined positive score >20, a high tumor mutational burden, a BRCA1 rearrangement, and an ATRX splice site mutation." (PMID 40377969, 2025). "Real-world database analyses suggest that BRCA1 or BRCA2 pathogenic variants are associated with increased PDL1 expression on tumor and immune cells and that biallelic inactivation correlates with the highest TMB." (PMID 40426860, 2025). "The tumor grade was particularly distinct between groups (p = 0.001), with BRCA1 patients being more associated with poorly differentiated tumors (75% vs. 30.3%)." (PMID 41002733, 2025). "Mutations in BRCA1/2 lead to deficiencies in this repair mechanism, resulting in genomic instability and an accumulation of mutations that drive tumor development." (PMID 40149262, 2025). "Drugs used for precision oncology can exploit synthetic lethal relationships; the best described are PARP inhibitors which preferentially kill BRCA1-deficient tumours preferentially over BRCA1-proficient cells." (PMID 40982437, 2025). "PARP inhibitors confer selective sensitivity against HRR‐deficient tumours and are a standard therapy in multiple tumour types for patients with deleterious germline mutations in BRCA1/2 and other DDR genes." (PMID 41018918, 2025). "The number of CD3+ and CD8+ tumor-infiltrating lymphocytes was increased in HR pathway deficient cells, whereas BRCA1/2 mutated tumors also showed increased infiltration of CD4+ cells." (PMID 40492861, 2025). "Central (in a designated reference laboratory)next-generation sequencing of tumor tissue and/or plasma identified 225 (53%) patients with BRCA1/2 mutations." (PMID 40806607, 2025). "BRCA1 encodes the BRCA1 protein, which is crucial for DNA repair and genome stability pathways, causing BRCA1 to be among the most well-studied tumor suppressor genes in the annotated human genome." (PMID 40909575, 2025). "BRCA1 was a tumor suppressor gene, and its encoded product was involved in DNA damage homologous recombination repair." (PMID 40404896, 2025). "Homologous recombination deficiency (HRD) resulting from inactivation of BRCA1/2 genes promotes chromosomal instability and renders tumor cells susceptible to platinum derivatives and PARP inhibitors (PARPi)." (PMID 41465280, 2025).
tumor (continued). "BRCA1 functions as a tumor suppressor, lowering the risk of tumorigenesis in tissues where it is normally expressed, by promoting apoptosis in damaged cells." (PMID 40141415, 2025). "More importantly, while BRCA1/2 deficiency is rare, T334 represents a potential target to induce HR deficiency in tumor cells and therefore expand PARPi indication to more patients." (PMID 41243969, 2025). "ARIEL3 introduced tumour homologous recombination deficiency (HRD) as an additional predictive marker for PARP inhibitors, with significant PFS benefits for both BRCA1/2 pathogenic variant carriers and patients with tumour HRD." (PMID 40069561, 2025). "Forty-one patients with HGSOC and a confirmed pathogenic variant in BRCA1/2 or other HCP gene on tumour testing were identified from the study period." (PMID 41300712, 2025). "There were statistically significant differences in age, tumor size, lymph node status, hormone receptor status, somatic BRCA1/2, and other homologous recombination-related gene mutations in the 3 HRD score groups at baseline (P < .05)." (PMID 38366907, 2024). "Analysis of large‐scale genomic alterations, loss of heterozygosity and tumour mutation burden identified six cases of high genomic instability (including four with pathogenic BRCA1 and BRCA2 mutations)." (PMID 39115191, 2024). "BRCA 1-Associated Protein-1 (BAP-1) is a pivotal anti-tumor protein that binds to the Breast Cancer 1 (BRCA-1) gene and plays a crucial role in deubiquitinating ubiquitin." (PMID 39796121, 2024). "In this study, an algorithm to assist decision-making for germline reflex testing of BRCA1/2 variants following tumor-only CGP is proposed." (PMID 39363506, 2024). "Collectively, these results suggest that DNA-PK-i acts together with PARP-i to suppress BRCA1-deficient tumor cell proliferation." (PMID 38682589, 2024). "Breast cancer susceptibility gene 1 (BRCA1) is a widely recognized gene that is responsible for suppressing tumor growth." (PMID 38224491, 2024). "The main resistance mechanism is restoring HRR capability, typically through secondary mutations in BRCA1/2 genes, that allow tumour cells to overcome the inhibition of DNA repair mediated by PARP." (PMID 39360040, 2024). "In this manuscript, we have shown a role for the histone H2AX in replication fork biology in BRCA1/2-deficient tumours." (PMID 38789420, 2024). "In some tumor samples, BRCA1 promoter methylation caused a decrease in BRCA1 expression, resulting in a loss of BRCA1 function." (PMID 39318358, 2024). "After describing BRCA1/2 alterations and reversion mutations that impact PARPi sensitivity and efficiency, we will further analyze the role of circulating tumor DNA (ctDNA) sequencing to detect them and improve therapeutic strategy." (PMID 38544832, 2024). "With further information on gBRCA1m and tumor BRCA1-PM, we redid the risk classification, and two distinct subgroups were identified." (PMID 38191387, 2024). "The combined treatment was well tolerated in vivo and resulted in tumor growth inhibition and a statistically increased survival in olaparib-resistant-BRCA1 mutated models." (PMID 39039067, 2024). "Though OLA treatment of either Flag- or Gata3-expressing Brca1-deficient tumor cells resulted in significantly less colonies than DMSO treatment, the colonies formed by Gata3-expressing cells were significantly more than those formed by Flag-expressing cells." (PMID 38627785, 2024). "Encouraging anti-tumor activity of platinum-based chemotherapy in a patient with mCRPC and DNA repair gene defects (i.e., BRCA1/2 mutations) has been found." (PMID 37934252, 2024).
tumor (continued). "The loss of tumor suppressors BRCA1 and BRCA2, which are involved in repairing double-strand breaks, can contribute to an abnormal accumulation of R-loops and cytosolic DNA, resulting in a heightened inflammatory response." (PMID 38473997, 2024). "The impact of BRCA1/2 mutation in HGSOCs has been extensively studied, with BRCA1/2 deficient tumours associated with a highly platinum sensitive phenotype and favourable patient prognosis." (PMID 38711848, 2024). "ABRAXAS1 is implicated in DNA repair and exerts tumour suppressive functions through its interactions with BRCA1." (PMID 39009827, 2024). "BRCA1 status, including pathogenic germline BRCA1 mutation (gBRCA1m), somatic BRCA1 mutation (sBRCA1m), and tumor BRCA1 promoter methylation (BRCA1-PM), was assessed using DNA from formalin-fixed paraffin-embedded tissue." (PMID 38191387, 2024). "BRCA1 DNA Repair Associated (BRCA1) is well-known in the field of oncology as it encodes a phosphoprotein which, among other things, acts as a tumour suppressor." (PMID 39595122, 2024). "For the 11 patients with HRD tumours, 2 patients had biallelic mutations (ATM and BRCA1 – both with PR), 7 patients had tumours with monoallelic HRD mutations, and 2 were unable to be determined." (PMID 38135713, 2024). "In conclusion, although both gBRCA1m and tumor BRCA1-PM alter BRCA1 gene transcription, they were associated with significantly different outcomes in young, node-negative TNBC patients." (PMID 38191387, 2024). "Depletion of Gata3 sensitized tumor cells to PARP inhibitor (PARPi), and reconstitution of Gata3 enhanced resistance of Brca1-deficient tumor cells to PARP inhibitor." (PMID 38627785, 2024). "PALB2 is a tumor suppressor gene with a role in the homologous recombination repair pathway, through interaction with both BRCA1 DNA repair associated (BRCA1) and BRCA2 DNA repair associated (BRCA2)." (PMID 38792412, 2024). "Nonetheless, ambiguity persists regarding the extent to which the functional assessment of HR activity can serve as a predictor for the susceptibility of tumor cells harboring BRCA1 or BRCA2 variants to the effects of PARP inhibitors and DNA-damaging agents." (PMID 38397209, 2024). "Additional investigation of our HR expression signature in independent CPTAC8 and TCGA9 HGSOC tumor cohort data showed a high quantitative correlation to BRCA1 or BRCA2 mutational status." (PMID 38480868, 2024). "Another eloquent aspect of our evaluation is related to the presence of the BRCA1/2 mutation, which was reported as positive in 18.8% (n = 44 cases) of the cases, thus confirming the hereditability of the tumor." (PMID 38612725, 2024). "In fact, despite being an important tumor suppressor in animals, in plants breast cancer susceptibility gene 1 (BRCA1) can maintain the DNA structural integrity." (PMID 38729985, 2024). "The BRCA1 is a tumor suppressor gene that encodes for the BRCA1 protein, which plays a vital role in DNA repair, cell cycle regulation, and the maintenance of genomic stability." (PMID 38543119, 2024). "Although both gBRCA1m and tumor BRCA1-PM alter BRCA1 gene transcription, they are associated with different outcomes in young, node-negative, chemotherapy-naïve TNBC patients." (PMID 38191387, 2024). "In one tumor sample, from a BRCA1 germline variant carrier (p.L82R), the BRCA1 VAF was 0.738, suggesting a loss of heterozygosity LOH event, or a clonal expansion." (PMID 39208653, 2024).